BRAF (B-Raf proto-oncogene, serine/threonine kinase)
Diseases named in the same sentence as BRAF in open-access papers (continued):
Sharing a sentence is not in itself a finding about the gene and the disease.
melanoma (continued). "Using genetically engineered mouse models, we demonstrate that the activating RAC1P29Smutation, present in up to 4% of melanoma cases, cooperates with BRAF as a driver of melanoma initiation and promotes BRAF inhibitor resistance." (PMID 31257073, 2019). "In melanoma, increased BRAF and cytoplasmic p300 expression was reported to be correlated with disease progression." (PMID 31010895, 2019). "Most importantly, SBI-756 eradicated BRAF-inhibitor resistant melanoma cells, as well as EIF4EBP null cancer cells, which are resistant to MTOR inhibitors." (PMID 30072418, 2019). "We employed SynGeNet to generate drug combination predictions for each of the four major genomic subtypes of melanoma (BRAF, NRAS, NF1, and triple wild type) using publicly available gene expression and mutation data." (PMID 30820351, 2019). "This review focuses on pre-clinical studies and early to phase III clinical trials to discuss the development of combined therapy based on BRAF inhibitors for BRAF-mutant advanced melanoma, as well as mechanisms of resistance to BRAF inhibitors." (PMID 31514399, 2019). "Melanoma is a lethal tumor because of its severe metastatic potential, and serine/threonine-protein kinase B-raf inhibitors (BRAFi) are used in patients harboring BRAF-mutation." (PMID 31783660, 2019). "The most frequent level 1 variants detected were identified in KRAS (colorectal cancer), EGFR (lung cancer), and BRAF (melanoma)." (PMID 30658646, 2019). "In melanoma, v-Raf murine sarcoma viral oncogene homolog B (BRAF) and MAPK (mitogen-activated protein kinase)/ERK kinase (MEK) inhibitors are widely used." (PMID 31086070, 2019). "The activated serine/threonine kinase BRAF mutant is a main driver of melanoma growth and progression and is a HSP90 client protein." (PMID 31861612, 2019). "First-line therapy of patients with BRAF mutant melanoma consists of treatment with a BRAF kinase inhibitor, which often produces a good initial response before resistance to therapy rapidly emerges." (PMID 31257073, 2019). "Within this testing model BRAF (serine/threonine-protein kinase B-Raf) and NRAS (neuroblastoma RAS viral oncogene homolog) mutations are sequentially investigated for diagnostic purposes, as 70% of melanomas detect BRAF and NRAS as common driver mutations." (PMID 31470637, 2019). "This systematic review and meta-analysis determines the association of BRAF and MEK inhibitor treatment with cardiovascular adverse events in patients with melanoma compared with BRAF inhibitor monotherapy." (PMID 31397860, 2019). "We show that treatment of BRAF‐mutant melanoma cell lines with trametinib induced cytotoxic autophagy and subsequent cell death." (PMID 30339727, 2019). "We provided evidence for the selection of BRAF-mutant melanoma cells during metastatic progression to the lung, intestine, adrenal gland and kidney." (PMID 31391014, 2019). "As a confirmation of this, an increased T cell infiltration and upregulation of melanoma antigens in patients treated with BRAF inhibitors has been demonstrated." (PMID 31581559, 2019). "Significantly, RTK signaling is present to a higher level in CRC than in melanoma, and one of them (EGFR) is mainly responsible for MAPK reactivation in BRAF-mutated mCRC, as shown in preclinical models." (PMID 31661924, 2019). "Our results support the validity of using combination therapy directed against RTKs overexpressed and hyperactivated in melanoma cells resistant to treatment with inhibitors of BRAF V600E." (PMID 31877948, 2019). "Several mechanisms involved in resistance to BRAF inhibitors (BRAFi) have been identified in melanoma." (PMID 30866509, 2019). "Another study confirmed the crucial role of fibronectin/β1 integrin signaling in melanoma adaptation to BRAF inhibition." (PMID 31109009, 2019). "Six ASC and two CSFs corresponded to melanoma patients progressing to immunotherapy and BRAF + MEK inhibitors, respectively, and they were all positive for the p.V600E mutation in BRAF." (PMID 31529604, 2019).
melanoma (continued). "The major drawback of melanoma therapy with BRAF and MAPK inhibitors is the innate and acquired drug resistance." (PMID 31040916, 2019). "The relationship between tumour driver mutation status and survival has been the subject of significant research efforts and it is now well appreciated that BRAF‐mutant tumours confer a poorer prognosis relative to BRAF wild‐type melanoma." (PMID 30511391, 2019). "This study provides a real-world description of how the introduction of new therapies such as immunotherapy and BRAF inhibitors is changing treatment strategies for melanoma in developing countries." (PMID 31138295, 2019). "Although various CDC7 pharmacological inhibitors have been developed exhibiting substantial antitumor activity as a single agent, no studies have been conducted on CDC7 inhibition as an alternative targeted therapy in BRAF inhibitors-resistant melanoma cells." (PMID 31578454, 2019). "In vitro studies demonstrate MEKi of BRAF‐mutant melanoma induced cytotoxic autophagy, followed by the emergence of CD271‐expressing subpopulations." (PMID 30339727, 2019). "In more recent years, anti-PD-1 for metastatic melanoma patients, and anti-BRAF/MEK for those with BRAF mutations, have had a profound effect on the survival of patients with advanced melanoma." (PMID 31614482, 2019). "Decrease in EMT markers (E-cadherin, YKL-40, N-cadherin, SNAI1) were seen with simultaneously decline in melanoma cells (BRAF, NAMPT) and stem cells (CD133, ABCB5) markers." (PMID 31126298, 2019). "Contrary to NRAS mutant cases, in BRAF-mutant melanomas MAFs were found to be significantly increased in visceral metastases compared to the primary due to the significantly higher levels in lung-, adrenal gland-, intestinal- and kidney metastases." (PMID 31391014, 2019). "Exposing transduced BRAFV600E A375 melanoma cells to the BRAF inhibitor vemurafenib yielded enrichment for known resistance gene NF1, as well as a handful of other genes including NF2." (PMID 31921397, 2019). "Inhibition of TGF-β signaling reverted EMT and restored BRAFi responsiveness in BRAF-mutant melanoma." (PMID 30979895, 2019). "Tumor-targeted inhibition of TAP also inhibited the growth of tamoxifen-induced tumors in the BRAF/PTEN melanoma model when used in combination with PD-1 Ab and Flt3 ligand." (PMID 31434881, 2019). "In a matched case–control setting we demonstrate that mitotic count and BRAF V600E immunohistochemistry significantly correlate with SNB positivity in cutaneous melanomas of intermediate thickness." (PMID 31039200, 2019). "This study aimed to determine mechanisms mediating the resistance of BRAF‐mutant melanoma cells to MEK‐specific inhibition and define innovative means through which to overcome such resistance in a clinical setting." (PMID 30339727, 2019). "Combinations of MEK and BRAF inhibitors with PD-L1 inhibitors demonstrated some promise in metastatic colorectal cancers and melanomas in early clinical trials." (PMID 31681559, 2019). "Crucially, pharmacological co-targeting of NFATc2 and EZH2 exerted significant anti-tumor activity not only against BRAF-mutant melanomas with intrinsic resistance to BRAF inhibitors, but even against NRAS-mutant and BRAF/NRAS wild type melanoma cells." (PMID 30710146, 2019). "We have recently reported that Cdh1 suppresses the BRAF/MEK/ERK signaling cascade in melanoma cells." (PMID 31420536, 2019). "Both the melanomas harbor KIT mutation in approximately 15% of the cases; BRAF or NRAS mutation is found in approximately 10–15% of acral melanoma, but these mutations are less frequent in mucosal melanoma." (PMID 30675668, 2019).
melanoma (continued). "In mutant BRAF melanoma cells, flow cytometry revealed that PLX4720 induced an increase of surface exposed CADM1." (PMID 30911007, 2019). "In the study of BRAF inhibition-resistant melanoma, the researchers found that the depletion of JNK and ERK 1/2 synergistically suppresses PD-L1 expression." (PMID 31507611, 2019). "The oncogenic function of macrophages and other tumor-infiltrating immune cells has been highlighted to confer BRAF inhibition resistance in melanoma cells." (PMID 31015455, 2019). "Inhibitors that specifically target constitutively active oncogenic V600E-mutant BRAF, have improved the therapy of melanoma patients whose tumours consist of cells that harbour V600E BRAF mutations." (PMID 35582596, 2019). "Taken together, experimental data in melanoma and in thyroid cancer suggest that BRAF-inhibitors not only exert direct effects on neoplastic cells, but also display an indirect anti-cancer action." (PMID 31762942, 2019). "To investigate how oncogenic BRAF regulates autophagy in melanoma, we treated A375 human melanoma cells, which express BRAFV600E, with PLX4720, a selective BRAFi15." (PMID 30979895, 2019). "The immune microenvironment represents a source of resistance to MAPK pathway inhibitors also via an increased number of tumor-associated macrophages, and TNFα and MITF (microphthalmia transcription factor) expression, observed in BRAF-mutant melanomas." (PMID 31652660, 2019). "Our first application of this mutagenesis approach was to derive human melanoma cells resistant to the BRAF inhibitor vemurafenib." (PMID 31208320, 2019). "The inhibition was reverted by BRAF or MEK inhibitors, but only when dendritic cells were co-cultured with melanoma cell lines carrying a BRAF V600E mutation." (PMID 31762942, 2019). "Magnolol‐induced a synergistic effect in combination with either BRAF/MEK inhibitors dabrafenib/trametinib or docetaxel at a lower concentration than usually applied in melanoma patients." (PMID 30793515, 2019). "A previous report has described how a BRAF inhibitor up-regulates PD-L1 in melanoma cells via c-Jun activation." (PMID 31341011, 2019). "In this respect, based on the identified correlations, we characterized the production of KYN, 3-HK, and KYNA in vitro using melanoma-derived BRAF wild type (wt) and BRAF V600E mutant cell lines cultured with primary CD4+ CD25− T-cells." (PMID 31434983, 2019). "BRAF or MEK1/2 inhibitors are cytostatic in melanoma and the surviving cells develop drug resistance." (PMID 31727888, 2019). "In support of a potential role of ITCH in controlling BRAF function, we found that in melanoma cells, depletion of ITCH suppressed proliferation and 3D spheroid formation of WM1346 cells." (PMID 31015455, 2019). "Boisvert-Adamo K and Aplin AE showed that two major survival pathways work in BRAF melanoma cells to provide a protection from anoikis: the B-RAF-MEK and the PI-3 kinase-AKT signaling." (PMID 31275384, 2019). "Recently, SOX10 has also been shown to regulate sensitivity to BRAF inhibitors in melanoma through compensatory mechanisms." (PMID 31416288, 2019). "Although BRAF has gained more attention in melanoma, RAF1 plays an important role in MAPK signaling." (PMID 30709382, 2019). "In comparison to DNA-based assays, these studies have shown a high sensitivity and specificity in detecting BRAF mutants, with a study reporting B-raf V600E protein expression as a novel prognostic marker in primary melanoma." (PMID 31835364, 2019). "We focused our work on NRAS and BRAF because there is sufficient genomic data available in mucosal melanoma." (PMID 31398831, 2019). "Altogether, our study demonstrated that long-term vemurafenib exposure in BRAF-mutant melanoma can lead to increased migration that correlates with elevated EGFR expression." (PMID 31514305, 2019).
melanoma (continued). "Today, immune checkpoint inhibitors (ICIs) represent a gold standard treatment in the first-line setting of several tumors, including non-small cell lung cancer (NSCLC), BRAF wild-type (WT) melanoma and metastatic renal cell carcinoma (mRCC)." (PMID 30991686, 2019). "The first combination therapy to be approved by the FDA was that of ipilimumab and nivolumab in 2015 for BRAF V600 wild type melanoma." (PMID 31640266, 2019). "In this study, we observed that AMPK activation by both uncouplers was significantly less in BRAFV600E melanoma compared with BRAF wild type as seen in the Western blot analyses." (PMID 30651927, 2018). "The BRAF mutations are present in about 40–50%, mutations of NRAS in 20% and of c-KIT in 1–3% of the melanomas." (PMID 30360441, 2018). "BRAF or MEK inhibition in BRAF-mutant melanoma cells leads to immediate crosstalk mechanisms, including the RAS-mediated activation of the PI3K pathway." (PMID 30237393, 2018). "In melanoma, point mutations N375S, T1010I and R988C, which were associated with NRAS and BRAF mutations, were detected." (PMID 29455657, 2018). "The treatments for melanoma have dramatically advanced in the recent years, and currently include targeted therapies against BRAF or MEK, and immunotherapy drugs." (PMID 30185782, 2018). "BRAF and MEK inhibitors (BRAFi/MEKi), the standard treatment for patients with BRAFV600 mutated melanoma, are currently explored in combination with various immunotherapies, notably checkpoint inhibitors and adoptive transfer of receptor-transfected T cells." (PMID 29346301, 2018). "K63-linked ubiquitination occurs in other kinases at sites homologous to K147 in IKKβ, including K578 in BRAF V600E, which serves as an oncogenic driver in melanoma and other cancers." (PMID 30335863, 2018). "MEK inhibitors have been evaluated in dozens of clinical trials as monotherapy and in combination with other agents, and to-date, have only been approved for use in combination with BRAF inhibitors in BRAF mutant melanoma (clinicaltrials.gov)." (PMID 29674704, 2018). "Several studies in primary melanomas have shown the prognostic significance of frequent somatic mutations, such as NRAS and BRAF." (PMID 30662871, 2018). "Despite no clear association in TCGA cases between KMT2D and conventional subtypes of melanoma such as NRAS or BRAF, a subsequent study showed that KMT2D deregulates specific enhancers and genes in NRAS-mutant melanoma." (PMID 30466474, 2018). "Although melanoma cells in vitro undergo cell death upon the treatment with the BRAF inhibitor PLX4720, these cells are resistant to PLX4720 treatment in vivo." (PMID 30101371, 2018). "At present, only 11 therapeutic choices against melanoma have been approved for clinical use, including BRAF and MEK inhibitors and therapeutic immune checkpoint inhibitors as well as IL-2 or Interferon alpha." (PMID 29371600, 2018). "To understand how oncogenic BRAF affects mitochondrial ROS production in melanoma, we studied the mitochondrial ROS‐producing oxidoreductase p66Shc, which is frequently overexpressed in tumors." (PMID 29624862, 2018). "Strikingly, Snail1-mediated suppression of CYLD played a crucial role in promoting RIP1 expression upon ERK activation, particularly, in melanoma cells with acquired resistance to BRAF inhibitors." (PMID 29880840, 2018). "The effects of combination of BRAF/MEKi and the SCD1 inhibitor MF-438 were monitored by spheroid-forming and proliferation assays on a panel of BRAF-mutated melanoma cell lines grown in 3D and 2D conditions, respectively." (PMID 30558661, 2018). "To evaluate the effectiveness of Chk1 inhibitors in melanoma therapy, we have generated BRAF inhibitor (PLX4032 or vemurafenib) resistant melanoma cell lines (A375-PLX-R and WM9-PLX-R) from A375 and WM9, respectively." (PMID 30100999, 2018). "We applied TEsmall to a novel dataset in which we compared the effects of BRAF inhibitor resistance on sRNA abundance in melanoma derived cell lines." (PMID 30349559, 2018).
melanoma (continued). "Loss of NF1 has been reported to result in resistance to various targeted tyrosine kinase inhibitors in a number of settings, including BRAF-mutant melanoma and EGFR-mutant lung cancer." (PMID 29435137, 2018). "In human mutant BRAF melanoma cells, the stemness transcription factor FOXD3 is rapidly induced by inhibition of ERK1/2 signaling and mediates adaptive resistance to RAF inhibitors." (PMID 29295999, 2018). "More importantly, both uncouplers were more potent to BRAF-inhibitor resistant melanoma as a consequence of drug-induced metabolic switch to OXPHOS phenotype." (PMID 30651927, 2018). "We previously reported on the efficacy of rMETase against a BRAF-V600E mutant melanoma patient-derived orthotopic xenograft (PDOX) nude mouse model and that rMETase sensitized the melanoma PDOX to temozolomide (TEM)." (PMID 29541401, 2018). "Target-specific drugs (e.g. Vemurafenib, Dabrafenib) were developed and initially approved for the treatment of BRAF V600E mutant melanomas, and have since been trialled first in malignant, and more recently in low-grade BRAF V600E mutant brain tumours." (PMID 29098416, 2018). "The BRAFCA-specific inhibitors have shown impressive beneficial effects on melanoma treatment but relapse occurs quickly in treated patients, and they are not effective against the ~40% melanomas that express wild-type BRAF." (PMID 29450192, 2018). "Another role of YAP/TAZ in therapy resistance of cancer was found in studies of BRAF V600E gain-of-function mutant melanomas." (PMID 30101371, 2018). "Insufficient cases were available to assess ITGAV transcripts as a biomarker in wildtype NRAS/BRAF melanoma." (PMID 30116025, 2018). "Since then, tons of studies have exploited the xenotransplantation of BRAFV600E human melanoma cells into nude mice which allowed a relatively easy and quick evaluation of the oncogenic role of activated BRAF and the potential of its targeting." (PMID 29534457, 2018). "Here we show that, the fraction of BRAF V600E in cfDNA can be used to monitor the response to BRAFi combination therapy in non-melanoma cancers and importantly, indicate disease progression median five weeks before radiological evidence." (PMID 30220966, 2018). "Although great advances have been achieved in melanoma treatment, including the recent introduction of targeted therapies such as vemurafenib, a BRAF inhibitor, and ipilimumab, an anti-CTLA-4 agent, new drugs and therapeutic strategies are urgently needed." (PMID 29899823, 2018). "The current targeted clinical treatment of melanoma consists of two key therapeutic areas, vemurafenib against BRAF mutant cells, and anti-immune checkpoint therapies, both of which display very visible clinical benefits." (PMID 29684045, 2018). "In terms of metabolism, melanomas that express mutant BRAF and that developed resistance against BRAF inhibitors display increased activity of mitochondrial oxidative metabolism, increased dependency on mitochondria for survival and higher levels of ROS." (PMID 30456204, 2018). "Nearly all patients with BRAF-mutant melanoma will progress on BRAF inhibitor monotherapy and combination BRAF/MEK inhibitor therapy within the first year of therapy." (PMID 30237495, 2018). "We and others have shown that MAPK inhibitors reverse also the metabolic phenotype by decreasing glycolytic activity and increasing mitochondrial oxidative phosphorylation (OXPHOS) of BRAF-driven melanoma cells." (PMID 29487283, 2018). "A number of molecular mechanisms, eventually co-existing, have been proposed in the attempt of explaining how melanoma cells adapt to prolonged inhibition of BRAF and MEK." (PMID 30558661, 2018). "More recently, RSK inhibition was shown to block cell proliferation and protein synthesis in BRAF/MEK inhibitor-resistant melanomas, establishing this pathway as a viable therapeutic strategy against chemoresistance." (PMID 30356079, 2018).